RHEB (Ras homolog, mTORC1 binding)
Description:
Small GTPase that acts as an allosteric activator of the canonical mTORC1 complex, an evolutionarily conserved central nutrient sensor that stimulates anabolic reactions and macromolecule biosynthesis to promote cellular biomass generation and growth. In response to nutrients, growth factors or amino acids, specifically activates the protein kinase activity of MTOR, the catalytic component of the mTORC1 complex: acts by causing a conformational change that allows the alignment of residues in the active site of MTOR, thereby enhancing the phosphorylation of ribosomal protein S6 kinase (RPS6KB1 and RPS6KB2) and EIF4EBP1 (4E-BP1). RHEB is also required for localization of the TSC-TBC complex to lysosomal membranes. In response to starvation, RHEB is inactivated by the TSC-TBC complex, preventing activation of mTORC1. Has low intrinsic GTPase activity.
Synonyms: RHEB2
Tractability: Small molecule: a structure with a bound ligand is known. Antibody: its Gene Ontology location is reachable by antibodies, with medium confidence. PROTAC: UniProt records ubiquitination sites on it; ubiquitination databases record sites on it; its protein half-life has been measured.
Gene: Protein-coding gene on chromosome 7 (151,466,012 to 151,520,120, reverse strand). Ensembl gene ENSG00000106615.
Subcellular location: Endomembrane system; Lysosome membrane; Golgi apparatus membrane; Endoplasmic reticulum membrane; Cytoplasm, cytosol
Pathways (Reactome):
Signal Transduction: Energy dependent regulation of mTOR by LKB1-AMPK; MTOR signalling; Regulation of PTEN gene transcription; mTORC1-mediated signalling
Autophagy: Macroautophagy
Cellular responses to stimuli: Amino acids regulate mTORC1
Gene Ontology:
Molecular function: GDP binding; GTP binding; GTPase activity; magnesium ion binding; protein binding; protein kinase activator activity; protein serine/threonine kinase activator activity; protein kinase binding
Biological process: cellular response to nutrient levels; positive regulation of TOR signaling; positive regulation of TORC1 signaling; regulation of type B pancreatic cell development; negative regulation of cold-induced thermogenesis; regulation of cell cycle; regulation of macroautophagy; signal transduction; small GTPase-mediated signal transduction; regulation of TOR signaling
Cellular component: endomembrane system; endoplasmic reticulum membrane; extracellular exosome; Golgi membrane; lysosomal membrane; postsynaptic density; membrane; plasma membrane; cytosol; spliceosomal complex; synapse
Genetic constraint (gnomAD): Loss-of-function variants: 1 observed, 0.6 expected, observed/expected ratio (o/e) 1.66, 90% interval 0.32 to 1.92. That is too few expected variants to judge how well the gene tolerates losing a copy. Missense variants: 7 observed, 7.21 expected, observed/expected ratio (o/e) 0.97, 90% interval 0.55 to 1.72. Synonymous variants: 5 observed, 2.71 expected, observed/expected ratio (o/e) 1.85, 90% interval 0.8 to 1.95.
Homologues: Orthologues: chimpanzee RHEB (100% identical), guinea pig RHEB (100% identical), rabbit RHEB (99% identical), mouse Rheb (99% identical), tropical clawed frog rheb (93% identical), chimpanzee RHEB (92% identical), macaque RHEB (91% identical), rat Rheb (91% identical), pig RHEB (91% identical), dog RHEB (88% identical). Paralogues in human: RHEBL1 (52% identical), RAP2B (40% identical), RAP2A (39% identical), RAP1B (38% identical), RAP1A (37% identical), RAP2C (37% identical), MRAS (36% identical), RALA (34% identical), RRAS2 (34% identical), DIRAS2 (34% identical), KRAS (34% identical), NRAS (33% identical), and 23 more.
Diseases named in the same sentence as RHEB in open-access papers:
RHEB is named in the same sentence as 85 diseases in open-access papers, as found by Europe PMC text mining. Sharing a sentence is not in itself a finding about the gene and the disease. The quoted sentences say what the papers report.
epilepsy (9 papers, 2017 to 2026). A brain disorder characterized by episodes of abnormally increased neuronal discharge resulting in transient episodes of sensory or motor neurological dysfunction, or psychic dysfunction. "Recently, we identified 2 de novo mutations in RHEB (c.110C>T (p.P37L) and c.202T>C (p.S68P)) in patients with ID, epilepsy, and megalencephaly, providing for the first time a clinically relevant link between RHEB and MCD." (PMID 34038402, 2021). "Here, we made use of the recently identified dominant-active mutation in Ras Homolog Enriched in Brain 1 (RHEB), RHEBp.P37L, to gain insight in the mechanism underlying the epilepsy caused by hyperactivation of the mTOR pathway." (PMID 34038402, 2021). "Focal cortical dysplasia type II results from somatic brain mutations in mechanistic target of rapamycin pathway activators MTOR, AKT3, PIK3CA and RHEB and is a major cause of drug-resistant epilepsy." (PMID 34632383, 2021). "For the most frequently mutated gene, RHEB, we show that hyperactivating mutations cause an ID syndrome with brain overgrowth and epilepsy." (PMID 29051493, 2017). "Given that RHEB mutations represent potentially druggable mTOR pathway targets, these findings have significant implications for individualized therapeutic strategies and precision epilepsy care." (PMID 41940182, 2026). "Finally, we demonstrated the ability to identify affected cell types in a patient with a RHEB somatic variant causing an epilepsy-associated cortical malformation." (PMID 36631516, 2023). "Furthermore, we present that de novo mutations in a key regulator of mTOR, RHEB, causes severe ID, epilepsy and megalencephaly in humans." (PMID 29051493, 2017). "Rapamycin and its analogs, that are currently in clinical use to treat epilepsy in TSC patients, curbed epileptiform activity in mouse models harboring TSC1/2, RHEB, MTOR, or PTEN mutations when administered long-term (>7-day)." (PMID 34899181, 2021). "In summary, here, we made use of a hyperactive RHEB mutant that was previously identified in patients with ID, megalencephaly, and epilepsy, as a model for human mTOR-related MCD-associated epilepsy." (PMID 34038402, 2021). "Seizures were particularly common in mice expressing mutant RHEB: whereas 20% (2/10) of mice expressing RHEB1-WT developed epilepsy, all (7/7) mice expressing RHEBp.P37L and 83% (5/6) of mice expressing RHEBp.S68P developed spontaneous seizures." (PMID 29051493, 2017). "Disruption of mTOR signaling due to variants in its repressors such as TSC1, TSC2, DEPDC5, PTEN or in its activators such as RHEB, and MTOR lead to a set of disorders characterized by early onset and often drug-resistant epilepsies called mTORopathies." (PMID 40792287, 2025). "We found that genes of the mTOR pathway (RPS6, RHEB, EIF4E) were highly expressed in the PY2 pyramidal neurons, consistent with the activation of the mTOR pathway in histopathological neurons in the epileptic focus of drug-resistant epilepsy." (PMID 40026248, 2025). "Thus, altered MAPK/ERK-FLNA function represents an mTORC1-independent mechanism that contributes to cortical malformations and epilepsy in TSC- and RHEB-related mTORopathies." (PMID 33897381, 2021).
breast carcinoma (7 papers, 2016 to 2024). "The gene mapping of 24 DEGs through PubMed, OMIM, MeSH, and PMC databases provided eight significant breast cancer associated genes: ID4, NCOA1, RHEB, PDZK1, PLAUR, AKC1R2, ANXA1 and SLIPI." (PMID 33593445, 2021). "Mutation of PIK3R5 and other genes (i.e. PRKCZ, PTEN, RHEB and RPS6KB1) have altered PI3K signaling pathway, which is the central pathway for both colorectal and breast cancers." (PMID 27161113, 2016). "We previously identified the mTOR pathway components RHEB and RPTOR as being positively regulated by EVI1 in metastatic breast cancer with stem cell-like features." (PMID 32012804, 2020).
hepatocellular carcinoma (5 papers, 2022 to 2025). A malignant tumor that arises from hepatocytes. "The overexpression of ATIC and RHEB was associated with metastasis and poor prognosis in hepatocellular carcinoma." (PMID 35573678, 2022). "Notably, CREB3L4 contributes to hepatocellular carcinoma development by promoting the RHEB-mTORC1 pathway and reducing sensitivity to chemotherapy drugs." (PMID 39254691, 2024). "Collectively, our study identifies RHEB as neddylation substrate of the UBE2F-SAG axis, and highlights the UBE2F-SAG axis as a potential target for the treatment of non-alcoholic fatty liver disease and hepatocellular carcinoma." (PMID 39762645, 2025).
tuberous sclerosis (5 papers, 2018 to 2023). Hereditary disease characterized by seizures, intellectual disability, developmental delay, and skin and ocular lesions. "With the tuberous sclerosis complex inactivated the RHEB GTPase now becomes active to induce mTORC1." (PMID 37240915, 2023). "The consequently released growth factors such as insulin and insulin-like growth factor (IGF) activate mTORC1 through phosphoinositide 3-kinase AKT-tuberous sclerosis-RHEB (PI3K-AKT-TSC-RHEB) signaling." (PMID 35215560, 2022). "Growth factors such as insulin and insulin-like growth factor (IGF) regulate mTORC1 through phosphoinositide 3-kinase (PI3K)-AKT-Tuberous sclerosis (TSC)-RHEB signaling." (PMID 30011848, 2018). "RHEB is inhibited by its GAP TSC1-TSC2 (tuberous sclerosis 1/2)." (PMID 32627660, 2021).
hepatitis B (4 papers, 2019 to 2023). "In conclusion, elevated circRNA-100338 activates mTOR signaling pathway in HCC via circRNA-100338/miR-141-3p/RHEB axis and associates with poor prognosis of hepatitis B-related HCC patients." (PMID 31157168, 2019). "Besides, RHEB expression was associated with higher cancer stages, higher mortality, tumor differentiation and pathological satellites in patients with hepatitis B-related HCC." (PMID 32807131, 2020). "It was shown that eIF5 is regulated by circ_100338/miR-141-3p/RHEB axis and higher expression of RHEB or eIF5 was an indicator of shorter OS in hepatitis B-related HCC." (PMID 37511619, 2023). "More importantly, activated mTOR signaling pathway by circRNA-100338/miR-141-3p/RHEB axis showed high correlation with poor prognosis in hepatitis B-related HCC." (PMID 31157168, 2019). "Integrated analysis of circRNA-100338, miR-141-3p, and target genes revealed that RHEB, a key regulator in mTOR signaling pathway, was the target of miR-141-3p in hepatitis B-related HCC." (PMID 31157168, 2019). "Particularly, the pulmonary metastasis rate was higher, and the overall survival was shorter in hepatitis B-related HCC with elevated expression of one or both of RHEB and EIF5 (P < 0.001)." (PMID 31157168, 2019). "In accordance with experiments in vitro, hepatitis B-related HCC tissues in circRNA-100338-high group also showed elevated expression of both RHEB, mTORC1, and EIF5, further demonstrating that circRNA-100338 could promote activation of mTOR signaling pathway." (PMID 31157168, 2019). "Finally, correlation analysis of RHEB and EIF5 expression with clinicopathological parameters of HCC patients revealed that the circRNA-100338, RHEB, and EIF5 were indicators of poor prognosis in hepatitis B-related HCC." (PMID 31157168, 2019).
prostate carcinoma (4 papers, 2020 to 2021). A carcinoma that arises from epithelial cells of the prostate gland. "For those molecules that were demonstrated to be correlated with poor prognosis in HNC patients, RHEB was also found overexpressed in prostate cancer, associated with poor prognosis, and promoted cell growth via the regulation of the mTOR signaling pathway." (PMID 33238517, 2020). "RHEB GTPase has also been shown to act as a proto-oncogene in prostate cancer and up to 4% of patients with prostate cancer carry RHEB gene amplification, however RHEB oncogenic mutations are rare (≤0.1% incidence)." (PMID 32630372, 2020). "The OS-related prognostic model was constructed based on the five ARGs (FAM215A, FDD, MYC, RHEB, and ATG16L1) and significantly stratified prostate cancer patients into high- and low-risk groups in terms of OS (HR = 6.391, 95% CI = 1.581– 25.840, P < 0.001)." (PMID 32264916, 2020). "Moreover, inhibition of RHEB can lead to the suppressed proliferation of prostate cancer cell lines." (PMID 32264916, 2020).
megalencephaly (3 papers, 2017 to 2021). A congenital abnormality in which the occipitofrontal circumference is greater than two standard deviations above the mean for a given age. "A previous study has shown that RHEB/P37L and RHEB/S68P cause an intellectual disability syndrome associated with megalencephaly." (PMID 34801548, 2021). "We report the mTOR activator gene RHEB as an ID gene that is associated with megalencephaly when mutated." (PMID 29051493, 2017). "Here, the authors identify de novo mutations in RHEB, an mTOR activator protein, in patients with intellectual disability associated with megalencephaly and find a role for RHEB in regulating neuronal soma size and migration in vitro and in vivo." (PMID 29051493, 2017).
autism (2 papers, 2013 to 2021). Persistent deficits in social interaction and communication and interaction as well as a markedly restricted repertoire of activity and interest as well as repetitive patterns of behavior. "A recent study reported that the P37L and S68P mutations in RHEB were associated with neurological disorders, such as autism." (PMID 34801548, 2021). "Two RHEB mutations (RHEB/P37L and RHEB/S68P) were recently reported as being involved in psychiatric disorders, such as autism." (PMID 34801548, 2021). "Since mounting evidence has established autism as a disorder of the synapses, we tested whether rare genetic variants in TSC1, TSC2, MYCBP2, RHEB and FBXO45, genes that regulate mTORC1 signaling and/or play a role in synapse development and function, contribute to the pathogenesis of idiopathic ASD." (PMID 23514105, 2013).
cervical cancer (2 papers, 2022). A primary or metastatic malignant neoplasm involving the cervix. "CircMYLK activates RHEB, a GTPase from the Ras superfamily, via downregulation of miR‐1301‐3p in cervical cancer cells." (PMID 35701309, 2022). "Our results are also consistent with those of a previous study in which miR-155 transfection in human nasopharyngeal cancer and human cervical cancer cells inhibited several components of PI3K-Akt-mTOR signaling, including RHEB, RICTOR, phosphorylated mTOR and Akt." (PMID 36076283, 2022).
colorectal cancer (2 papers, 2019 to 2021). A primary or metastatic malignant neoplasm that affects the colon or rectum. "In more detail, Tian and co-workers reported the inhibition of cell proliferation and initiation of apoptosis in colorectal cancer cells via silencing of the RHEB gene." (PMID 33800955, 2021).
endothelial dysfunction (2 papers, 2023 to 2025). In vascular diseases, endothelial dysfunction is a systemic pathological state of the endothelium (the inner lining of blood vessels) and can be broadly defined as an imbalance between vasodilating and vasoconstricting substances produced by (or acting on) the endothelium. "In senescent HUVECs, upregulated miR-155-5p mediated endothelial dysfunction through NF-κB/endothelial nitric oxide synthase (eNOS) axis and inhibited the proliferation of ECs by targeting Ras homolog enriched in brain (RHEB) expression." (PMID 37469665, 2023).
Intellectual disability (2 papers, 2017 to 2021). "We analyzed the intellectual-disability-related RHEB/P37L and RHEB/S68P mutants using IP-RP-HPLC." (PMID 34801548, 2021).
liver cancer (2 papers, 2021 to 2025). An epithelial or non-epithelial malignant neoplasm that arises from the liver. "We next investigated the biological consequence of RHEB-K169R mutation in liver cancer cells." (PMID 39762645, 2025). "NEDD8 conjugation of lysosomal small GTPase RHEB controls mTORC1 activity, autophagy and hepatic cancer progression." (PMID 39762645, 2025). "The expression of ATIC, HDAC1, RHEB, SPNS1 and TMEM74 in liver cancer tissues was significantly higher than that in normal liver tissues." (PMID 34803509, 2021). "Thus, our study revealed a novel mechanism by which neddylation activates the RHEB-mTORC1 signaling pathway, and provided proof-of-concept evidence that the UBE2F-SAG axis could be an attractive anti-liver cancer target." (PMID 39762645, 2025). "Importantly, under unstressed physiological condition, endogenous SAG bound to endogenous RHEB, but neither SAG nor RHEB binds to UBE2F or mTOR in these liver cancer cell lines." (PMID 39762645, 2025).
ovarian carcinoma (2 papers, 2025). A malignant neoplasm originating from the surface ovarian epithelium. "Indeed, in ovarian cancer cells, the GTPase RGS10 accelerated the hydrolysis of GTP bound to RHEB, thereby inactivating RHEB and mTORC1 activity." (PMID 39762645, 2025). "In contrast, RHEB and SQSTM1, known negative regulators of autophagy, showed decreased expression in resistant samples, indicating a strong correlation between autophagy activation and the development of cisplatin resistance in ovarian cancer." (PMID 41502518, 2025).
Alzheimer disease (1 paper, 2018). A progressive, neurodegenerative disease characterized by loss of function and death of nerve cells in several areas of the brain leading to loss of cognitive function such as memory and language. "Another example for the involvement of RHEB in neurodegenerative diseases is Alzheimer disease (AD)." (PMID 30558189, 2018).
angiomyolipoma (1 paper, 2017). A neoplasm with perivascular epithelioid cell differentiation often associated with tuberous sclerosis. "Next, we generated focal deletion of the NRE3 region within the endogenous RHEB promoter in CRL4004 angiomyolipoma cells using CRISPR/Cas9." (PMID 29184052, 2017). "We hypothesized that alterations in RHEB and HES1 expression are required for neuronal differentiation of angiomyolipoma cells." (PMID 29184052, 2017). "However, both angiomyolipoma cell lines 621–101 and CRL4004 used in this work have multiple common features such as mTORC1 hyperactivation, differentiation abnormalities, binding of Notch1 to the RHEB and HES1 promoters, and oscillation of RHEB and HES1 mRNAs and proteins." (PMID 29184052, 2017).
asthma (1 paper, 2019).
brain tumor (1 paper, 2025). "One of these inherited variants was a duplication of RHEB, maternally derived, in a patient with ASD who had a brain tumor." (PMID 39610113, 2025).
clear cell renal cell carcinoma (1 paper, 2015). "Using publicly available tumor genome sequencing data, we identified several point mutations in MTOR and its upstream regulator RHEB (Ras homolog enriched in brain) in patients with clear cell renal cell carcinoma (ccRCC), the most common histology of kidney cancer." (PMID 26255626, 2015).
colon cancer (1 paper, 2022). "For example, Bacteroides could promote colon cancer progression via inducing the stemness of colon cancer cells and activating RHEB/mTOR signaling pathway." (PMID 35592677, 2022).
cystadenoma (1 paper, 2012). A benign or borderline cystic epithelial neoplasm arising from the glandular epithelium. "We suspect that the complete absence of Tsc2 in these Tsc2+/− cystadenoma lesions leads to strong activation of mTORC1 due to constitutive high levels of RHEB-GTP, which makes these lesions resistant to the lesser effect of Raptor phosphorylation." (PMID 22363765, 2012).
endometrial cancer (1 paper, 2018). Primary or metastatic malignant neoplasm involving the endometrium (mucous membrane that lines the endometrial cavity). "The oncogenic RHEB mutant Y35N was identified in human cancers including renal cancer and endometrial cancer." (PMID 29320991, 2018).